CD4 (CD4 molecule)
Diseases named in the same sentence as CD4 in open-access papers (continued):
Sharing a sentence is not in itself a finding about the gene and the disease.
bacterial infections (continued). "In the Aquitaine cohort, a study focusing on severe bacterial infections showed that these events were more frequent in patients with a CD4/CD8 ration< 0.8." (PMID 27548257, 2016). "We show conclusively here that cholinergic signalling through the M3R is a major contributor to immunity to parasitic and bacterial infection, and that in its absence CD4 T cell responses are significantly impaired." (PMID 25629518, 2015). "Combined, these data clarify the role of OX40 signals for a physiological cohort of antigen-specific CD4+ T cells during an acute bacterial infection." (PMID 24771127, 2014). "Conversely, there have been many studies highlighting the important of CD4+ T cells in providing protective immunity against bacterial infection." (PMID 25386180, 2014). "It will provide a basis to study in detail the role of CD4+ T-cell differentiated subsets, in particular CD4+ CTLs and their importance in the immune control of bacterial infections." (PMID 24367519, 2013). "The bacterial infections are common in this study population because HIV is also associated with substantial dysregulation of humoral immunity, since CD4 lymphocytes regulate B cell differentiation and indirectly affect antibody production and phagocytosis." (PMID 24312650, 2013). "Th1 T cells: CD4+ T cells that express T-helper 1 (Th1)-type cytokines, such as interferon-γ (IFNγ), and facilitate cell-mediated immune responses against viral and bacterial infections." (PMID 23828644, 2013). "Particularly notable is the fact that one of these patients, who also had a bacterial infection during the 4th follow-up ambulatory visit, showed the highest percentage of CD4+NKG2D+ T cells (12.6%)." (PMID 23947399, 2013). "Previous report identified TNF as a negative regulator of Th1 type immune response during intracellular bacterial infection and showed an uncontrolled expansion of spleen CD4+ T cells, a marked increase of circulating and antigen-specific IFN-γ in TNF−/− mice." (PMID 22666310, 2012). "For all other schedules it seems that both CD4+ and provirus are relevant in determining fatal outcomes of the bacterial infection." (PMID 22558348, 2012). "It has been reported that CD4+ T-cells are important for development of long term immunity to bacterial infections." (PMID 19340309, 2009). "Additionally, we found upregulation of Tnfsf8, the ligand for CD30, which is expressed by activated CD4+ T cells and required for differentiation of both Th1 and Th17 cells during bacterial infections." (PMID 40307618, 2025). "However, there is limited information on the role of CD4+ CTL in the defence against bacterial infections." (PMID 40939292, 2025). "In models of bacterial infection, genetic deletion of CD30 or CD 30L leads to a decrease in the long-term ability to control the pathogen that is associated with the loss of long-lived CD4+ T cells secreting IFNg and defective CD8+ T cell memory cells." (PMID 38793771, 2024). "High HIV RNA load may impair the function of immune cells, such as CD4+ T cells and natural killer cells, which play crucial roles in the defense against bacterial infections." (PMID 38988810, 2024). "Moreover, studies in vivo confirmed that CD4+-IF1-KO mice have a limited Th1 immune response against bacterial infection compromising mice survival and highlighting the essential role played by IF1 in metabolic reprograming and proliferation of T lymphocytes." (PMID 38799559, 2024). "Overall, the results support that upon bacterial infection, CD4+ lymphocytes devoid of IF1 cannot proliferate and polarize properly to the different effector subsets in vivo, hence compromising the antibacterial immune response what results in increased mortality." (PMID 38799559, 2024). "Additionally, MHC class II binding is upregulated, which implies the involvement of CD4-positive T cells that would then stimulate an antibody response against bacterial infection." (PMID 39366656, 2024).
bacterial infections (continued). "However, the candidates commonly used for adaptive immune cell characterization, such as CD79a and IgM for B cells and CD3 and CD4 for T cells, were minimally influenced by bacterial infection." (PMID 39011038, 2024). "In addition, in bacterial infections in peripheral tissues, many proliferating CD4+ T lymphocytes leave the draining lymph nodes and migrate to the infected tissue through the bloodstream." (PMID 38137455, 2023). "To further evaluate Th1 and Th17 responses in mice infected with T4 alone versus PR8/T4, we analyzed expression of IL-17A+CD4+ T cells in lung lymphocytes by intracellular cytokine staining following in vitro stimulation with PMA/ionomycin 6 days after bacterial infection." (PMID 37222516, 2023). "In addition, it influences innate immunity in keratinocytes,and treatment with CD4-PP is able to clear bacterial infections ininfected keratinocytes." (PMID 37132993, 2023). "Notably, we found that mTORC1 regulates the development of CD3+CD4-1+IFN-γ+ T cells in tilapia during intracellular bacterial infection at least by promoting the proliferation of CD3+CD4+ T cells and expression of the transcription factors STAT1 and T-bet." (PMID 36282845, 2022). "However, evidence from viral and bacterial infections suggests that CD4+ T-cell help is essential for eliciting CD8+ T-cell responses." (PMID 36177012, 2022). "Collectively, this may in part explain the poor recruitment and ultimate retention of S. aureus specific CD4+ T cells in the lung following bacterial infection." (PMID 35637249, 2022). "Our findings showed that CD4+ T cell levels were associated with neither the systemic inflammatory response nor bacterial infection." (PMID 35637935, 2021). "This change in CD4+ T cell count may have been due to a pronounced systemic inflammatory response that may have been induced by surgery or bacterial infection." (PMID 35637935, 2021). "CD4+ T cells positively influence the activity of phagocytic cells in rickettsial infection; major cytokines produced by activated CD4+ T cells in bacterial infections have been reported to be IFN-γ and TNF-α, related to a potentiated activity on nitric oxide-mediated killing by macrophages." (PMID 33233869, 2020). "For example, upon C. trachomatis infection, CD4+ cells become activated, begin to proliferate with a characteristic Th1 response, secreting large amounts of interferon γ required to aid in clearing bacterial infection." (PMID 31231361, 2019). "In contrast to other teleosts, Atlantic cod (Gadus morhua) has an expanded repertoire of MHC-I and TLR components, but lacks the MHC-II, the invariant chain/CD74, and CD4+ T cell response, essential for production of antibodies and prevention of bacterial infectious diseases." (PMID 31231379, 2019). "Moreover, increased sodium promotes the development of IL-17 producing CD4+ T cells (Th17 cells), which are critical effector cells in response to extracellular bacterial infections and are also important mediators of autoimmune inflammatory diseases." (PMID 29410520, 2018). "Here, we provide first evidence that activated CD11chiMHCII+CD4+ pDCs may represent a check-point during the differentiation of DCs from progenitor cells in the bone marrow during systemic bacterial infection." (PMID 29218051, 2017). "The effects of antiretroviral therapy on risk of severe bacterial infections in people with high CD4 cell counts have not been well described." (PMID 28063815, 2017). "Most people with parasitic or bacterial infection had CD4 in the range of 100–300 cells/μL." (PMID 27795876, 2016). "Furthermore, Clec4a4−/− mice displayed the enhanced anti-bacterial responses of CD4+ T cells following bacterial infection when compared with WT mice." (PMID 27068492, 2016). "We can speculate that in conditions of sub-optimal humoral responses, the role of CD4 T cells, and in particular Th1/Th17 responses, become more evident in contributing to protection against bacterial infection." (PMID 26441955, 2015).
bacterial infections (continued). "Most cases were known to be HIV-positive at IMD diagnosis and half of them continued to have low CD4 counts at IMD diagnosis, making them generally susceptible to serious bacterial infections, including the less virulent meningococcal capsular groups such as MenW and MenY." (PMID 26654248, 2015). "Although the individual did suffer from Kaposi’s sarcoma, she controlled common Herpes virus infections, and was not unduly susceptible to bacterial infections, despite the absence of recall CD4 memory responses." (PMID 24782861, 2014). "IVIg might in this situation contribute to control of bacterial infections and microbial translocation, and possibly support normalization in immune activation levels and CD4 counts similar to what we have observed here in CVID." (PMID 24130688, 2013). "Finally, we provide evidence that CD4+CTL activity is not limited to antiviral T cell responses but also extends to acute bacterial infections." (PMID 23565245, 2013). "CD4+ T lymphocytes play a critical role in the host immune responses during bacterial infection." (PMID 21269437, 2011). "CD4+ T cells are critically involved in clearing persisting bacterial infection." (PMID 21264307, 2011). "An expected change observed was the increased abundance of OspC in the RpH culture, representing an important virulence factor given that it can bind tick salivary protein Salp15 (a protein that inhibits the activation of CD4+ T cells) that modulates host responses during bacterial infection." (PMID 21072190, 2010). "The bacterial agents could be distinguished from the viral agents by the T cell result; CD4+ T cells reacting in bacterial infection, and the CD8+ T cells dominating for the viruses." (PMID 20626864, 2010). "Interestingly, a recently published study found that activation‐induced downregulation of miR‐29a/b facilitated Ifng production in activated CD4+ T cells and natural killer (NK) cells to resist intracellular bacterial infection and that miR‐29a/b directly targeted Ifng." (PMID 40873647, 2025). "S14), as CD8+ T cells recognize and destroy infected cells by releasing various cytotoxins and CD4+ cells produce cytokines to assist cytotoxic T lymphocyte activation or support the development of humoral immunity driven by B cells to fight against bacterial infections." (PMID 38578994, 2024). "Regarding Th17 immunity against bacterial infection, Lgals3−/− mice exhibited normal clearance of C. rodentium, indicated by no obvious differences between WT and Lgals3−/− mice in body weight, bacterial load, colon length, and colonic CD4+ T cells, including CD4+IL17A+ cells and Tregs." (PMID 39504243, 2024). "Importantly, CD4+ T cells could secrete IL-22, which can aid in intestinal resistance to bacterial infection." (PMID 37067423, 2023). "Furthermore, lung CD4+ TRM cells are essential for protection against bacterial infection." (PMID 33968018, 2021). "Days 7 and 14 were chosen because CD4 T cell responses against B. pertussis develop rather slowly with a peak in lungs at around 14 dpc, compared with the CD4 T cell responses to other bacterial infections such as Listeria monocytogenes or Salmonella, which peak around 7 dpc or earlier." (PMID 30105030, 2018). "However, there is growing evidence that in intracellular bacterial infections, where protection is largely mediated by CD4+ T cells, the role of the PD-1/PD-L1 pathway may be less straightforward." (PMID 21509782, 2011). "In this study, bacterial infection, FIB, and CD4+ T cell count were identified as the most important factors affecting NPM recurrence and were used for model development." (PMID 39820962, 2025). "Additionally, a low CD4 nadir in HIV infection has been independently associated with significant B cell impairment that is not fully restored with antiretroviral treatment, predisposing patients to more invasive bacterial infections than the general population." (PMID 41441706, 2025).
bacterial infections (continued). "Analysis of disease preference revealed that Tfh, Th2, and proliferating CD4+T cells were enriched in mild patients, while a Treg subset (CD4_05_Treg) expanded predominantly in severe patients, suggesting that a Tfh and Th2 response might be involved in controlling the bacterial infection." (PMID 39757231, 2025). "Lymphocytes are heterogeneous cell populations in which CD3+CD4+ and CD3+CD8+ subsets appear to assume important functions under bacterial infections that occur in PDT." (PMID 36829785, 2023). "The aim of the present study was to evaluate the influence of a modified mesh structure with variation in filament linking on the occurrence of bacterial infection that is indicated by the occurrence of CD68+, CD4+, and CD8+ cells in two different materials." (PMID 37509722, 2023). "As expected, mice treated with MP-MENP plus laser irradiation exhibited the highest infiltration of effector T helper cells (CD4) and cytotoxic T lymphocyte (CD8) at the site of bacterial infection." (PMID 38115145, 2023). "This is followed by a marked activation and expansion of CD4+ and CD8+ T cells that play an essential role in controlling bacterial infection." (PMID 36605208, 2022). "In this model, IL-17-producing CD4+ TRM cells recruit neutrophils to the lung, which is crucial for protecting the host against bacterial infection." (PMID 33968018, 2021). "Bacterial infections were found to be prevalent in the early and middle part of the clinical staging of HIV with CD4+ cell count ranging from 200-660 cells/mm3." (PMID 34513432, 2021). "By the transgenic mice model, soluble OPN has been observed an induction to proliferation of effector CD4+ and CD8+ cells in cell-mediated reactions, while OPN-/- mice demonstrated severely impaired cell-mediated immunity to viral and bacterial infections." (PMID 33264357, 2020). "MHC class II-restricted CD4+ T cells support memory CD8+ T cell responses and are important for protective immunity against bacterial infections, such as M. tuberculosis s, S. aureus, and S. typhimurium." (PMID 32858901, 2020). "Lower levels of CD3+ (p < 0.001), CD4+ (p = 0.008) and CD8+ (p = 0.003) T-lymphocyte counts were found in the group suffering bacterial infections." (PMID 31849894, 2019). "In conclusion, our results demonstrate that CD39 is upregulated on conventional CD4+ and CD8+ T cells at sites of acute infection and inflammation, and that CD39 dampens responses to bacterial infection." (PMID 29742141, 2018). "Recent studies suggest that both CD4+ T cells and IFN-γ play critical roles in combating bacterial infections." (PMID 28224119, 2017). "In a murine model of burns with bacterial infection, APS was found to suppress the expression of Foxp3 by CD4+CD25+ Treg and to activate Th1 cell-mediated immunity." (PMID 26693207, 2015). "Levels of NK cells producing cytokines were not altered or even lower after iron supplementation, which is in line with a diminished differentiation of CD4+ T helper type 1 (Th1) cells and the expression of IFN-γ after an iron loading before bacterial infection." (PMID 39877355, 2024). "Naive CD4+ T cells can be differentiated into Th17 cells that produce IL-17, Th1 cells that produce TNF-α and IFN-γ, and Th2 cells that produce IL-4, and during intracellular bacterial infection." (PMID 35663972, 2022). "Given the scale of the cellular response of this patient, we investigated whether the large expansions of CD4+ and CD8+ T-cells were due to a T-cell response targeting SARS-CoV-2, the secondary bacterial infection or to bystander T-cell activation." (PMID 33331820, 2020). "We show that CD4+ T-cell-dependent antigen presentation generates central memory CD8+ T cells (CD44+CD62LhighCCR7+) in vivo in a natural repertoire environment, in the course of a bacterial infection." (PMID 29147022, 2017).
bacterial infections (continued). "Only mice that received H-2Kb CD4+ T cells activated OT-I CD8+CD45.1+ T cells, which confirmed tpCD4+ T-cell-mediated transphagocytosis and antigen presentation in the course of an in vivo bacterial infection." (PMID 29147022, 2017). "Furthermore, cross-reactive cellular immune responses include multifunctional CD4+ and CD8+ T cells underscoring the importance of multiple layers of immune mechanisms involved in the protection against this bacterial infection." (PMID 28570603, 2017). "Given the better understanding of the role of non-CD4+ immune cells in early control of severe bacterial infections, including Mtb and non-typhoidal Salmonella, we assessed beneficial effects of boosting these cell types with IL-2/anti-IL-2 complexes." (PMID 27391012, 2016). "For both bacterial infections and cardiovascular events, the CD4/CD8 ratio did not add predictive information to the CD4 cell count." (PMID 27548257, 2016). "This may have reduced bacterial infections in HEU infants and, coupled with the anti-inflammatory properties of cotrimoxazole, had an impact on CD4 T-cell activation and PD-1 expression." (PMID 26569505, 2015). "Although this last finding was unexpected, it could be explained by the CD8 T cell depletion observed in severe bacterial infections, rather than by a decrease in CD4 counts." (PMID 41441706, 2025). "Since bacterial infection and autoimmune response are responsible for OLP initiation, we established two cell models in human oral keratinocytes (HOKs) by means of LPS or activated CD4+ T cells’ secretion treatment 6, to mimic the microenvironment of OLP in vitro." (PMID 31907356, 2020). "Under these conditions, our inability to detect the intracellular expression of IFN-γ or very little amounts of TNF-α in CD4+ and CD8+ T cells may be in part the consequence of T cell exhaustion that has been observed before in chronic viral and bacterial infections, and in tumors." (PMID 32013893, 2020). "CD4+ and CD8+ T-cell responses targeting P. aeruginosa peptides could also be detected, and increased over time concomitant with the onset of the recurring bacterial infection." (PMID 33331820, 2020). "Thus, IL-2c (IL-2 bound by S4B6) expands effector cells (CD8 and CD4 T cells and NK-cells), and can lower pathogen burden in bacterial infections without signs of VLS." (PMID 30379932, 2018). "Of note, for CD4+ T cells which are frequently involved in immune responses to bacterial infections, for example via IL17 production, no up-regulation of the activation-associated CD8α molecule could be found." (PMID 28559930, 2017). "Furthermore, the patients with any signs of bacterial infections were not excluded, and we did not perform subgroup analyses of the CD4+ T cell levels in different etologies." (PMID 26287969, 2015). "A higher incidence rate of bacterial infections (14.48 per 100 person-years) was observed among the Taiwan patients on cART with CD4 counts of less than 200 cells/mm3 who were not on PCP prophylaxis compared with an incidence rate of 5.56 per 100 person-years for those taking prophylaxis." (PMID 22281054, 2012). "IL-17 is normally produced by CD4+ T cells, although it might also arise from CD8+ T cells and in some cases even from macrophages, neutrophils or eosinophils, as a necessary step in the normal immunity against bacterial infections in the airways." (PMID 21615971, 2011). "Therefore, the lack of complete recovery of CD161+ CD4+ T cells in peripheral blood, despite initiation of ART at the earliest possible stage, could contribute to the susceptibility to bacterial infections seen in ART-treated individuals." (PMID 33322496, 2020). "Hence, bacterial infection or inflammatory markers did not seem to directly influence the recruitment of CD161+CD4+ T cells in the cervical compartment, but elevation of IFN-γ and IL-1α contributes to maintaining high level of CD161 cell surface expression in the FRT." (PMID 28894259, 2017).